IGF1R (insulin like growth factor 1 receptor)
Diseases named in the same sentence as IGF1R in open-access papers (continued):
Sharing a sentence is not in itself a finding about the gene and the disease.
tumor (continued). "Among the miRNA with reduced expression in SMZL, nine can target CAV1, including miR-199a, miR-376, and miR-485, and may promote tumor progression by inducing the overactivation of transcriptional factors (IGF1R for miR-376a; IKKβ and NFκB pathway for miR-199a)." (PMID 34590593, 2021). "Anti-IGF-1R therapy may inhibit tumor growth and contribute to immunotherapy in LIHC and KIRC." (PMID 34804946, 2021). "Importantly, activation of GR promoted phosphorylation of IGF-1R in xenograft tumours." (PMID 34272384, 2021). "Interestingly, an ongoing clinical trial (NCT03316638) is currently testing clinical safety and maximum tolerated dose (MTD) of W0101, a unique IGF1R—targeted antibody—drug conjugate, designed to deliver a cytotoxic auristatin derivative to IGF1R overexpressing tumor cells." (PMID 34440844, 2021). "Furthermore, the authors showed that miR-143/145 inhibited CRC cell proliferation in vitro, by inhibiting IGF1R expression highlighting their tumor suppressor activity in CRC, the importance of IGF1R in CRC pathogenesis, and underlying a novel regulatory network to fine-tune cell proliferation." (PMID 34484116, 2021). "Therefore, the distinct prognostic value of changeable IGF-1/IGF-1R expression across different cancers may result from its synthetic effect of immune suppressive activity and tumor suppressive activity in each cancer type." (PMID 34804946, 2021). "IRAIN via targeting IGF1R could alter the phenotypes of MDA-MB-231 tumor cells." (PMID 33768092, 2021). "Additionally, increased IGF-1R signaling was observed in AXL-low mtEGFR-expressing NSCLC tumor cells treated with osimertinib and knockout of IGF-1R sensitized AXL-low NSCLC cells to osimertinib, suggesting that IGF-1R drives cell survival in the presence of osimertinib." (PMID 34830794, 2021). "Therefore, we performed RT‐qPCR assays to identify target mRNAs that were regulated by both PCAT6 and IGF2BP2 in these tumor‐related mRNAs and found that IGF1R was the most downregulated mRNA both in PCAT6‐ and IGF2BP2‐knockdown PC‐3 cells compared with control PC‐3 cells." (PMID 34185427, 2021). "However, the relationship between IGF-1/IGF-1R overexpression and tumor immunity was still unclear." (PMID 34804946, 2021). "Therefore, exosomal circRNAs may also affect tumor immune microenvironment and promote tumor progression by regulating IGF-1R." (PMID 33613113, 2021). "It is noteworthy that, when CRC cells were transfected with miR-9 mimic, they expressed less phospho-IGF1R, cyclin B1, and N-cadherin, all involved in cell cycle progression while E-cadherin expression was increased; this latter is involved in cell-cell adhesion and tumor suppression." (PMID 34484116, 2021). "We next determined whether human tumor OPCs require IGF1R and are sensitive to IGF1R inactivation." (PMID 33173731, 2020). "However, suppression of IGF2/IR/IGF-1R inhibits the metastatic ability and tumor growth of erlotinib-resistant CC cells in vivo and in vitro, and linstinib-mediated IGF-1R inhibition also markedly suppressed the proliferation of human liver myofibroblasts (HLMF) through reduction of α-SMA." (PMID 32708604, 2020). "Since osimertinib is a selective inhibitor of mutated EGFR in tumor cells and spares wild type EGFR expressed mainly in host cells, the feasibility of a transient combination of IGF-1R inhibitor with osimertinib may be more superior to first or second generation EGFR-TKIs." (PMID 32929081, 2020). "Moreover, we detected the IGF-1R expression by IHC on these tumour samples." (PMID 31988347, 2020). "Therefore, our finding leads to the novel proposition that tumor OPCs may use IGF1R to activate both pathways for their maximal fitting in the in vivo condition." (PMID 33173731, 2020). "However, reintroduction of exogeneous IGF1R could partially restore the tumor initiating capacity of this cell line." (PMID 33173731, 2020).
tumor (continued). "To further address whether IGF1R plays a role in the progression of tumor OPCs in vivo, we utilized the cell line from the CKO_NG2‐CreER_IGF1R (flox/flox) model where IGF1R was largely knocked out and examined its growth after grafted into the brains of NOD‐SCID mice." (PMID 33173731, 2020). "In particular, Plasmodium infection can significantly decrease MMP-9 expression by regulating IGF-1, which might signal intracellularly through the PI3 and MAPK pathways after binding to IGF-1R on the cell surface and thereby increase the expression of MMPs in tumor-bearing mice." (PMID 32972437, 2020). "Indeed, PDGF and FGF2 was unable to rescue the growth of tumor OPCs after IGF1R was knocked down." (PMID 33173731, 2020). "Therefore, many Furin substrates like IGF1R and IR influence tumor progression at a late stage." (PMID 32962246, 2020). "Hence, reduction of IGF1R may lead to enhanced cellular stress and cytokine production, with ensuing promotion of an aggressive tumor microenvironment." (PMID 32391121, 2020). "Patients whose tumors express IGF1R but not IRA may, however, benefit from IGF1R inhibitors, which might explain why these compounds caused long-lasting tumor response in two cases in clinical trials." (PMID 33260481, 2020). "Importantly, we demonstrate a synergistic/additive effect of the combinatorial therapy of PPP1R1A and insulin-like growth factor 1 receptor (IGF-1R) inhibition on decreasing ES cell proliferation and migration in vitro and limiting xenograft tumor growth and metastasis in vivo." (PMID 32477459, 2020). "Since proliferation was successfully inhibited in both cell lines by linsitinib, it appears that ERα(Ser167) phosphorylation might be a more relevant IGF‐1R‐dependent phosphorylation site on ER to drive tumor cell proliferation capacity than phosphorylation of ERα(Ser118)." (PMID 31490549, 2020). "Thus, targeting IGF-1R appears as a reasonable rationale for tumor treatment." (PMID 32843616, 2020). "Moreover, assessment of the downstream targets of IGF-1R suggests that tumor regression may be dependent on the inhibition of ERK signaling." (PMID 31751381, 2019). "Therefore, aberrantly activated IGF-1R may decrease radiosensitivity in a self-protective feedback loop model in tumor cells." (PMID 31467485, 2019). "In addition, tumor cells were also reported to overcome IGF1R inhibition in an EGFR-dependent manner, indicating that EGF signaling could be another way mediating IGF1R blockade resistance." (PMID 30422809, 2019). "Thus, miR-9 is a tumor-suppressive microRNA that may inhibit the IGF1R pathway to regulate the targeting of cyclin B1 and N-cadherin, and increase E-cadherin in CRC cells in HG-concentration medium." (PMID 30965609, 2019). "Similarly, the IGF-1R survival pathway contribute to Gefitinib resistance and synergistically inhibition of IGF-1R could strengthen the anti-tumor effect of Gefinitib." (PMID 31998131, 2019). "Furthermore, DLEU1 knockdown impaired tumour growth in vivo by regulating miR‐133a/IGF‐1R axis." (PMID 31207081, 2019). "We hypothesize that coffee may play a role for breast cancer prognosis through modulation of tumor IGF1R protein expression in human breast cancer, and that the impact of coffee may be modified by BMI given that both coffee and BMI influence circulating IGF-1 levels in women." (PMID 29928262, 2018). "IGF-1R expression levels are rarely related to a mutation in the corresponding gene; the few known cases describe heterozygote forms associated to growth retardation and not to neoplasia." (PMID 30111747, 2018).
tumor (continued). "Notably, the IGF-1R gene is elevated in the majority of cancers and may be an attractive therapeutic target for anticancer therapy because elevated IGF-1R mediates the signalling amplification of a major oncogenic pathway in neoplasia." (PMID 29712908, 2018). "Therefore, to investigate IGF1R as a mediator of IGF2 survival signaling, and as an potential therapeutic target in MRT, we determined whether blocking IGF1R inhibited tumor cell growth in vitro." (PMID 28521298, 2017). "Since we have only performed RNAseq we can, of course, not exclude other genomic mutations that were missed in our analysis and that could contribute to MG tumor development and explain the IGF1R-driven enhancement of tumor development/progression in our models." (PMID 28173837, 2017). "Therefore, miR-497 and miR-99a may play important suppressive effects on tumor growth controlled by IGF1R/mTOR signaling pathway and would be both biological and clinical targets for future HCC research." (PMID 28624790, 2017). "The inverse relation between IGF-1R expression and immune cell functions, observed here in the clinical bone metastases, suggests that long-term IGF-1R inhibition may have the potential to stimulate endogenous T cells activity and thus tumor immunosurveillance." (PMID 28447314, 2017). "Citrate’s effect in several tumor models may be explained by its broad actions on signaling pathways (in particular those involving IGF-1R and its downstream events), intermediary metabolism (both glycolysis and TCA cycles), and immune response (T-cell infiltration and cytokine changes)." (PMID 28674429, 2017). "Therefore, we hypothesized that citrate treatment may suppress tumor growth via inhibition of IGF-1R phosphorylation (and activity), which might increase tumor-infiltrating T lymphocytes and pro-inflammatory cytokines." (PMID 28674429, 2017). "In this study, we demonstrated that ectopic expression of miR-99a in HepG2 and Hep3B cell lines and tumor models could suppress cell proliferation, apoptosis, invasive, metastasis and tumor growth by targeting IGF1R and mTOR, which were consistent with the previous observation." (PMID 28624790, 2017). "Targeting of all three receptors may be more efficient since dual inhibition of InsR and IGF1R with tyrosine kinase inhibitor OSI-906 in combination with ER downregulator fulvestrant more effectively suppress hormone-independent tumor growth than either drug alone." (PMID 29234306, 2017). "Therefore, CDK4/6- and IGF-1R-inhibitors were tested on this patient's tumor in the PDOX model." (PMID 27286459, 2016). "In addition, in most cell lines IGF-1 could partially rescue the growth inhibitory effects of metformin, implying that simultaneously inhibiting IGF-1R might further improve the anti-tumor effect of metformin." (PMID 27488947, 2016). "Furthermore, combinational therapy targeting EGFR and IGF1R could synergistically inhibit cell viability, induce apoptosis in vitro and inhibit tumor xenografts growth in vivo." (PMID 27105537, 2016). "The decline of IGF-1R expression in the tumor during TAC treatment observed in our study might reflect chemotherapy efficacy, as patients with a decline in IGF-1R expression showed a significantly better pathological response than tumors with no change or an increase in expression." (PMID 26738606, 2016). "Thus, high levels of IGF1R expression on the cell surface may be taken as a feature which would suggest a given tumor is likely to respond to inhibition of IGF signaling." (PMID 27532210, 2016).
tumor (continued). "Moreover, the correlative expression of the IGF-1R/mTORC2/Akt pathway with constitutive activation of p-Akt (Ser 473) in his tumor could have played a dual role in ARMS." (PMID 27323832, 2016). "Therefore, we demonstrated that tumor may compensate strategies targeting IGF1R by activating alternative EGFR downstream signaling pathway." (PMID 27105537, 2016). "Additionally, since the cetuximab and IMC-A12 treatments were limited to only three times at 3-d intervals, differential up-regulation of EGFR or IGF-1R after the termination of treatments may have contributed to accelerated tumor growth." (PMID 25355701, 2015). "In this scenario the insulin analogues could act either as a tumor initiator by transforming benign or (pre)neoplastic cells, which often express increased levels of IRA and IGF1R, or as a tumor promoter by stimulating the increased growth potential of these cells." (PMID 26187749, 2015). "Thus, our hypothesis is that IGF1R CAR T cells can kill IGF1R+ tumor cells even with a low level of surface expression." (PMID 26173023, 2015). "Therefore, it could be seen that the IGF-1R blockade appeared to induce the tumour infiltration of various stromal cells." (PMID 26465273, 2015). "The delayed tumor onset after genetic ablation of Furin in the salivary glands could be explained by the partially impaired processing of the insulin-like growth factor 1 receptor (IGF1R) in the salivary glands." (PMID 26167473, 2015). "Because activation of IGF-1R-mediated signaling has been associated with cancer cell resistance to anti-EGFR therapy and also to RT 16,17, cotargeting EGFR and IGF-1R pathways in conjunctions with RT is expected to yield a better outcome in controlling tumor growth." (PMID 25355701, 2015). "Notably, silencing of IGF1R reduces tumor initiating ability of the xenografts." (PMID 25964777, 2015). "Numerous studies indicated that IGF-1R may be a promising target for tumor therapy." (PMID 26307972, 2015). "In addition, membrane IGF1R correlated with larger tumor size and with younger patient age at diagnosis, suggesting that IGF1R may be associated with a negative prognosis." (PMID 24392142, 2014). "Surveying the online algorithms miRanda and TargetScan, we found that IGF-1R, a central receptor protein to facilitate tumor development mainly by AKT and MAPK pathways, bears miR-503 target site in its 3′UTR region, thus may serve as a potential target gene of miR-503." (PMID 24378652, 2014). "Indeed, a combination of molecules inhibiting IGF1R signalling and promoting demethylation might be a possible therapeutic strategy worth to be further investigated in this tumour." (PMID 25427715, 2014). "Then, later in life and if IGF-1R inhibitors are truly specific for senescent cells, the physician may subscribe such inhibitors for prevention of senescence-induced microenvironmental changes that might promote tumor survival and progression." (PMID 24937130, 2014). "Taken together, our results demonstrated that miR-503 is a tumor suppressor in GBM with multiple aspects of antitumor effects partially mediated by post-transcriptional downregulation of insulin-like growth factor-1 (IGF-1R) expression, thereby interfering with the PI3K/AKT pathway." (PMID 24378652, 2014). "Therefore, IGF-1R axis inhibitors combined with metformin may act synergistically to kill tumor cells, since metformin delays and prevents feedback from the IGF-1R signaling pathway." (PMID 25289085, 2014).
tumor (continued). "Subsequently, IGF-1R and its natural ligands were demonstrated to regulate multiple cellular functions essential for the malignant phenotype including cellular proliferation, survival, anchorage-independent growth, tumor neovascularization, migration, invasion, and metastasis." (PMID 24276851, 2014). "Thus, in the present case it seems, the proliferation of tumour cells might be rather supported by increased effect of IGF1, IGF2 and IGF1R homodimer associations, than IGF1, IGF2 and INSR-IGF1R heterodimer associations or INSR effects on IRS1." (PMID 25496518, 2014). "Targeting the IGF1R pathway may be a promising strategy for overcoming gefitinib resistance in EGFR mutation-positive NSCLC induced by lung CSCs and microenvironment factors such as tumor hypoxia." (PMID 24489728, 2014). "Therefore, miR-133a mimics may be promising small compounds in regulating IGF-1R signaling in tumor cells." (PMID 24816813, 2014). "Thus, co-targeting the PI3K/Akt/mTOR pathway and its upstream signal, IGF-1R may prove to have synergistic anti-tumor effects and is worthy of further investigation." (PMID 23663564, 2013). "However, in other tumor cell types IGF-1R is dispensable for the induction of radiation resistance, suggesting that IGF-1R is anti-apoptotic in specific cell types and that the underlying mechanism(s) of radiation resistance in other cancer cells remain unresolved." (PMID 24205274, 2013). "Hence, IGF-1R (like EGFR) may play a role in maintaining intracellular glucose levels in tumor cells in a kinase-independent manner." (PMID 23531874, 2013). "If high IGF1R expression is limiting lifespan by induction of tumorigenesis, one might expect IGF1R levels to be inversely correlated with lifespan in all organs that have a high incidence of neoplasia." (PMID 23651613, 2013). "Otherwise the patient’s tumor might be resistant to IGF1R inhibitor therapy." (PMID 23922674, 2013). "Indicating the importance of the IGF-1R in oncogenesis in general, the receptor seems indispensable for transformation, and its overexpression in murine models may even increase the incidence of tumor formation." (PMID 22348393, 2012). "Interestingly, only in this cell line 0.5 μM PPP was able to downregulate the IGF-1R, which would fit with the hypothesis that the IGF-1R has to be downregulated/degraded for extensive tumor cell kill." (PMID 22159423, 2012). "Thus, such a tumor environment where IGF-1 may directly and indirectly stimulate tumor expansion seems optimal for validating the therapeutic potential of developed antagonists to the IGF-1R signal in MM." (PMID 22348393, 2012). "Notably, p-STAT3(Tyr705) was detected in a very minor component of the tumoral nuclei in the initial biopsy and was variably expressed in the post-anti- IGF1R treatment biopsy, ranging up to approximately one-half of the tumor cells in one microanatomical region." (PMID 21494688, 2011). "Although IGF1R is necessary for response to anti-IGF1R therapies, it is uncertain whether there is a relationship between patient response and levels of IGF1R expression in the tumour." (PMID 19491901, 2009). "AVE-1642 Alexa 680 could monitor this downregulation of IGF1R by diminished tumour fluorescence." (PMID 19491901, 2009). "Moreover, we demonstrated that both KSIMM cells as well as KS tumours express IGF-1R." (PMID 15812560, 2005). "The TNBCvax group (a combination of all three antigens) and the individual IGF-1R, HIF-1α, and TOP2A vaccination groups showed significantly reduced tumor growth rates compared to the CpG control group." (PMID 40969744, 2025). "In a separate TMA cohort containing tumor tissues from CCA patients, IGF1R expression levels were evaluated and patients were stratified into IGF1RHigh and IGF1RLow groups based on the median IHC score." (PMID 41275311, 2025).